RNU6-1029P (RNA, U6 small nuclear 1029, pseudogene)
Gene: Small nuclear RNA gene on chromosome 2 (197,447,745 to 197,447,851, forward strand). Ensembl gene ENSG00000206836.
Homologues: Orthologues: chimpanzee U6 (99% identical). Paralogues in human: RNU6-48P (93% identical), RNU6-12P (92% identical), RNU6-13P (92% identical), RNU6-140P (92% identical), RNU6-25P (92% identical), RNU6-32P (92% identical), RNU6-33P (92% identical), RNU6-41P (92% identical), RNU6-49P (92% identical), RNU6-1 (91% identical), RNU6-1122P (91% identical), RNU6-1124P (91% identical), and 1288 more.